LRRK2 (leucine rich repeat kinase 2)
Diseases named in the same sentence as LRRK2 in open-access papers (continued):
Sharing a sentence is not in itself a finding about the gene and the disease.
Parkinson disease (continued). "Genetics: If experience with parkin- and LRRK2-related parkinsonism suggests that pathology can be inconclusive, can genetics ultimately define diagnosis?" (PMID 24619848, 2014). "Leucine-rich Repeat Kinase 2 (LRRK2) is one of the genes that is most frequently involved in Parkinson's disease (PD)[e-1]." (PMID 24816003, 2014). "Recently, the Gray group developed a kinase inhibitor targeting Leucine-rich repeat kinase 2 (LRRK2), which is implicated in both genetically predisposed and sporadic Parkinson’s disease." (PMID 24885928, 2014). "Scans were available from 37 cases of monogenetic Parkinson's disease (7 glucocerebrosidase (GBA) mutations, 8 alpha-synuclein, 3 LRRK2, 7 PINK1, 12 Parkin)." (PMID 23935950, 2013). "As is abundantly obvious from this brief summary of our current understanding of LRRK2 biology, there are many challenges still to be met before we have a complete picture of LRRK2s function and how this is perverted in Parkinson's disease." (PMID 23938341, 2013). "As we have learned more about the genetics of LRRK2, the importance of this gene in Parkinson's has become ever clearer." (PMID 23938341, 2013). "The importance of leucine-rich repeat kinase 2 (LRRK2) to mature neurons is well-established, since mutations in PARK8, the gene encoding LRRK2, are the most common known cause of Parkinson’s disease." (PMID 23754980, 2013). "Genes including ATP13A2, DJ-1, GIGYF2, HTRA2, LRRK2, PARK2 (parkin), PINK1, SNCA and UCHL1 were associated with either autosomal dominant or recessive form of Parkinson's disease." (PMID 24688734, 2013). "The objective of this study was to evaluate the pathology time course of the LRRK2 knockout rat model of Parkinson’s disease at 1-, 2-, 4-, 8-, 12-, and 16-months of age." (PMID 24244710, 2013). "In patients with Parkinson’s disease (PD), FRs have been associated with several genes, such as SNCA, parkin, DJ-1, PINK1 and LRRK2, with a defect in complex I of the mitochondrial electron-transport chain and oxidative stress in substantia nigra." (PMID 23344052, 2013). "Further support, albeit indirect, of a role for LRRK2 in Wnt signaling comes from studies investigating altered gene expression in animal models of Parkinson’s disease." (PMID 23754980, 2013). "Proof of principle has been demonstrated by work in Parkinson's disease, where RNAi sequences to LRRK2 and SNCA were incorporated into the miR-1224 mirtron backbone." (PMID 24133413, 2013). "Leucine Rich Repeat Kinase 2 (LRRK2) is one of the most important genetic contributors to Parkinson's disease." (PMID 23916833, 2013). "This is of particular interest for LRRK2 whose biochemical properties, such as its kinase activity, have been proposed as potential targets for disease modifying Parkinson's disease therapy." (PMID 22952686, 2012). "Deletion of LRRK2 or expression of Parkinson’s disease mutants leads to increased autophagosomes and protein aggregates." (PMID 21994779, 2011). "Leucine rich repeat kinase 2 (LRRK2) has been identified as a Parkinson's disease (PD) gene responsible for parkinsonism with a clinical course essentially identical to that in idiopathic PD." (PMID 21858031, 2011). "They will also stimulate further research tounderstand how phosphorylation of Ser910 and Ser935 is controlled by LRRK2,and establish any relationship to development of Parkinson's disease." (PMID 20659021, 2010). "The ROCO proteins have recently received considerable attention because in humans the family member LRRK2 is involved in familial and some cases of sporadic Parkinson's disease." (PMID 20576132, 2010). "The discovery of pathways in which LRRK2 is involved will hopefully lead to a better understanding of the pathomechanisms of familial and sporadic forms of Parkinson's disease." (PMID 21048939, 2010). "Other proteins with leucine-rich repeats like LINGO-1 and LRRK2 have been shown to play a role in structural and functional integrity of neurons involved in Parkinson's disease." (PMID 18445277, 2008).
Parkinson disease (continued). "As the PD and DLB cases we investigated are sporadic and patients carrying the common LRRK2 mutations seem to share a typical late-onset disease presentation, our findings suggest a universal role of LRRK2 in etiology and pathogenesis of parkinsonism." (PMID 17137507, 2006). "Mutations in five genes have been shown to cause parkinsonism: α-synuclein (dominant), parkin (recessive), DJ-1 (recessive), PINK1 (recessive) and LRRK2 (dominant)." (PMID 17187665, 2006). "Identifying prodromal Parkinson's disease among LRRK2 carriers is critical yet challenging." (PMID 42147151, 2026). "LRRK2 is one of the therapeutic targets in Parkinson's Disease (PD)." (PMID 41977401, 2026). "Among study participants with and without a mutation in the LRRK2 gene, Parkinson’s patients were found to be biologically older by Horvath’s clock, and was further associated with an earlier age of onset, but not greater disease severity." (PMID 41488274, 2025). "A comparison of LRRK2 parkinsonism cases with asyn aggregates to sporadic cases with asyn aggregates is needed to determine the influence of the pathogenic variant itself on phenotype among those with asyn aggregates, and this analysis is underway in the PPMI cohort." (PMID 40114783, 2025). "Our findings support the view that pharmacological treatment of Parkinson's patients with inhibitors of LRRK2 may alleviate the symptoms of this neurological disorder." (PMID 40397198, 2025). "Loss of neuroprotection in this brain region is a common feature of LRRK2 and GBA1 mutations and may represent a convergent pathway contributing to Parkinson’s." (PMID 40737317, 2025). "Investigating genetic protection against Parkinson’s disease in non-manifesting carriers of LRRK2 mutations by CRISPR/Cas9-based genome edition." (PMID 40832425, 2025). "Furthermore, SAA positivity has been reported in asymptomatic carriers of LRRK2 mutations and individuals with PRKN mutations, despite a reduced prevalence of Lewy pathology in postmortem studies of these genetic forms of Parkinsonism." (PMID 40496124, 2025). "In addition to clinical-stage drug candidates, the table also includes preclinical PROTACs, such as a BCL-XL degrader for solid tumors and a LRRK2 degrader for Parkinson’s disease." (PMID 40574056, 2025). "Approximately 5–10% of patients, however, develop a “monogenic form of Parkinson’s Disease”, which is caused by pathogenic variants in SNCA, LRRK2, and VPS35, genes exhibiting autosomal dominant inheritance, along with PRKN, PINK1, and DJ-1, genes which follow autosomal recessive inheritance." (PMID 40564955, 2025). "In this study, we have demonstrated several characteristics that are different in LRRK2-associated parkinsonism cases with versus without evidence of asyn aggregates in the CSF." (PMID 40114783, 2025). "A total of 148 LRRK2 parkinsonism cases (86% with G2019S variant), 46 negative and 102 positive for CSF alpha-synuclein seed amplification assay, were included." (PMID 40114783, 2025). "Aberrant activation of LRRK2 via this pathway may be of relevance in both Parkinson’s and Crohn’s diseases." (PMID 39812709, 2025). "The role of Drp1 has been identified as a contributing factor in the pathogenesis of Parkinson’s disease, with a substantial body of evidence demonstrating the involvement of α-Syn, DJ-1, LRRK2, PINK1, and Parkin in the regulation of mitochondrial dynamics and homeostasis through the Drp1 pathway." (PMID 40463912, 2025). "A research study conducted proteomics analysis of CSF from healthy controls, Parkinson’s disease (PD) patients with and without the LRRK2 G2019S mutation, and individuals with non-manifesting LRRK2 G2019S." (PMID 40426665, 2025). "Interestingly, flies expressing mutant forms of LRRK2 often show reduced lifespan, altered movement, and neuronal degeneration similar to that observed in patients with Parkinson’s disease." (PMID 40076730, 2025).
Parkinson disease (continued). "Our findings suggest that pharmacological strategies aimed at enhancing transporter activity via LRRK2 could ameliorate pathological conditions not only in Parkinson's disease but also across a spectrum of neurodevelopmental and neurodegenerative disorders." (PMID 39655696, 2025). "Pathogenic mutations in other Parkinson’s disease genes, including Rab32 and VPS35, also enhance LRRK2 signaling, underscoring the importance of understanding how upstream cellular processes regulate LRRK2 activation." (PMID 41332754, 2025). "Our objective was to compare clinical and biomarker features, and rate of progression over 4 years of follow-up, among LRRK2-associated parkinsonism cases with and without in vivo evidence of alpha-synuclein aggregates." (PMID 40114783, 2025). "Targeting this site could represent a strategy to enhance PPM1H-mediated dephosphorylation of LRRK2 substrates, offering a potential therapeutic approach to counteract LRRK2-driven Parkinson’s disease." (PMID 40463289, 2025). "If the outcomes are positive, it could demonstrate how effective LRRK2 is at treating Parkinson’s disease." (PMID 40650193, 2025). "Astrocytes are known to be become reactive in Parkinson’s disease that includes neuroinflammation, and several genes implicated in Parkinson’s are expressed in both astrocytes and neurons (e.g., PARK7, SNCA, PLA2G6, ATP13A2, LRRK2, PINK1, and PARK2)." (PMID 40972575, 2025). "Three potential ligands for the WDR40 domain of LRRK2 could be identified, providing valuable insights in the pursuit of novel therapeutic interventions for Parkinson’s disease." (PMID 40999521, 2025). "The interaction between TLRs and LRRK2 in microglial activation represents a fascinating and critical aspect of neuroinflammatory mechanisms, particularly in neurodegenerative diseases such as Parkinson’s disease." (PMID 40309866, 2025). "Nevertheless, sex-specific differences may be present in LRRK2 R1628P parkinsonism; therefore, it is important that sex-specific effects are characterized and evaluated in a future study." (PMID 40332013, 2025). "The European and Asian LRRK2 disease-causing mutational spectrum does not appear to play a major role in Parkinson’s disease in West African and African admixed populations." (PMID 39867380, 2025). "As LRRK2 is expressed in immune and intestinal epithelial cells, it may serve as a molecular link between dysbiosis, inflammation, and neurodegeneration in Parkinson's disease." (PMID 41346294, 2025). "Better understanding the link between genetic and epigenetic factors earlier in the course of the disease may present new therapeutic avenues to help delay LRRK2 R1628P parkinsonism." (PMID 40332013, 2025). "Dissecting the mechanistic links between specific LRRK2 mutations and early non-motor symptoms in Parkinson’s disease is key to clarifying how distinct genetic models converge or diverge in their pathogenic trajectories." (PMID 40949874, 2025). "The robust links between LRRK2 and Parkinson’s disease have motivated the development of candidate therapeutic strategies designed to limit LRRK2 kinase activity and have raised important questions about the functions of LRRK2 and how they contribute to disease-causing cellular processes (5, –7)." (PMID 40758897, 2025). "In Alzheimer’s disease (AD), personalized medicine helps predict risk and guide targeted treatments through APOE ε4 and other genetic variants, while in Parkinson’s Disease (PD), mutations in the GBA and LRRK2 genes influence disease course and therapy response." (PMID 41590228, 2025). "Human Pegivirus infection may influence Parkinson’s disease by altering immune signaling, metabolism, and key genes, potentially affecting LRRK2 and non-LRRK2 carrier patients differently." (PMID 40626361, 2025). "CAF interacts with specific genetic variants such as MAPT, SLC2A13, LRRK2, ApoE, NOS2A, GRIN2A, CYP1A2, and ADORA2A, which may influence the risk of developing Parkinson’s Disease (PD)." (PMID 40650030, 2025).
Parkinson disease (continued). "Given previously reported links between cGAS–STING dysregulation and Parkinson’s disease–associated genes, we tested whether STING controls LRRK2 activity." (PMID 39812709, 2025). "The LRRK2 6099G > A (Gly2019Ser) mutation leads to the most frequent substitution in Caucasians, which typically explains 0.5–2.0% of cases of SPD and 5% of familial Parkinsonism." (PMID 37644186, 2024). "This will allow investigation of differences in various biologic processes in LRRK2-associated parkinsonism asyn positive and negative cases in the future." (PMID 39108519, 2024). "Studies to date indicate that individuals with LRRK2-associated parkinsonism with and without evidence of asyn aggregates are largely clinically indistinguishable, with a few noted differences." (PMID 39108519, 2024). "It is known that Parkinson’s disease has a genetic origin (i.e., mutations in the PARK genes encoding alpha-Synuclein, DJ-1, PINK, LRRK2, etc.)in 5–10% of patients, causing so-called early-onset PD and that most of these cases are idiopathic and associated with aging." (PMID 38474065, 2024). "Although subtle prodromal signs may be missed, including hyposmia, REM sleep behavior disorder, and orthostasis, the expressivity (defined as the variability in the presentation of clinical phenotypes) of LRRK2 parkinsonism is as variable as idiopathic PD." (PMID 39062657, 2024). "Sex differences in LRRK2-parkinsonism cases are particularly notable." (PMID 39108519, 2024). "The Parkinson’s disease case–control GWAS LRRK2 rs76904798 variant was also not genome-wide significant (OR = 1.02, 95% CI = 0.88–1.18, P = 0.7759)." (PMID 38978726, 2024). "Furthermore, a large-scale study is currently underway in the United States, which aims to determine the frequency of variants in the seven most common genes associated with Parkinson’s disease: GBA, LRRK2, PRKN, SNCA, PINK1, PARK7, and VPS35." (PMID 38397244, 2024). "LRRK2 mutations have been found in individuals without manifest Parkinson’s disease, in which compensatory changes in the serotonergic system were described." (PMID 38256187, 2024). "Our objective was to compare clinical and biomarker features, and rate of progression over 4 years follow-up, among LRRK2-associated parkinsonism cases with and without in vivo evidence of alpha-synuclein aggregates." (PMID 39108519, 2024). "DBS has shown promise in monogenic PD and parkinsonism patients like LRRK2." (PMID 39619277, 2024). "Interestingly, the authors also report cell type-specific enrichments of Alzheimer’s and Parkinson’s disease gene expression with aging, including LRRK2." (PMID 38811759, 2024). "Interestingly, recent studies have revealed that mitochondrial PARK7 (Parkinson’s disease 7) and LRRK2 (leucine-rich repeat kinase 2) genes are related to an increased risk of IBD." (PMID 39000169, 2024). "Our investigation aimed to ascertain whether a correlation exists between mPRS and CSF asyn SAA status among LRRK2 parkinsonism cases." (PMID 39108519, 2024). "One limitation of this study is that LRRK2 G2019S KI mice do not spontaneously develop Parkinsonism; therefore, it is imperative to develop a PD model with the LRRK2 G2019S mutation and further evaluate its susceptibility to tumorigenesis in the future." (PMID 38607004, 2024). "The common LRRK2 mutation G2019S enhances NSF kinase activity, potentially disrupting SV dynamics through abnormal phosphorylation of NSF and contributing to the manifestation of Parkinson’s symptoms." (PMID 39498393, 2024). "Understanding the impact of PTMs, particularly phosphorylation, on LRRK2 is essential for unraveling the intricate molecular mechanisms contributing to Parkinsons disease, offering potential insights into therapeutic strategies targeting these specific modifications." (PMID 38960968, 2024). "The underlying biology in LRRK2-parkinsonism cases without evidence of alpha-synuclein aggregates requires further investigation." (PMID 39108519, 2024).
Parkinson disease (continued). "On the other hand, there is a reported case of LRRK2-associated parkinsonism that did not demonstrate postmortem Lewy pathology but who demonstrated asyn aggregates on brain homogenate by asyn SAA28." (PMID 39108519, 2024). "LRRK2 is one of the most promising drug targets for Parkinson’s disease." (PMID 38263358, 2024). "We have separated these into 4 categories, namely diseases (e.g., Parkinson’s, Alzheimer’s), enzymes (e.g., kinases, phosphatases), organelles (e.g., Golgi, lysosomes), and pathways (e.g., LRRK2, PINK1), that are listed in Dataset S2, and these can readily be updated and added to." (PMID 38324566, 2024). "Several Parkinson’s disease causative mutations have been found in proteins functioning in synaptic vesicle endocytosis (e.g., SYNJ1, DNAJC6 (DnaJ heat shock protein family (Hsp40) member C6), SNCA (synuclein alpha) and LRRK2 (leucine rich repeat kinase 2))." (PMID 37067454, 2024). "Many studies that have investigated genetic modifiers in LRRK2-associated parkinsonism did not account for underlying pathology." (PMID 39108519, 2024). "LRRK2-associated parkinsonism cases without asyn aggregates are more likely to be female, normosmic, to have relatively milder motor manifestations, and to exhibit less functional decline." (PMID 39108519, 2024). "In this study, we have demonstrated several characteristics that are different in LRRK2 associated parkinsonism cases with vs without evidence of asyn aggregates in the CSF." (PMID 39108519, 2024). "Variants in seven genes (LRRK2, GBA1, PRKN, SNCA, PINK1, PARK7 and VPS35) have been formally adjudicated as causal contributors to Parkinson’s disease; however, individuals with Parkinson’s disease are often unaware of their genetic status since clinical testing is infrequently offered." (PMID 39074992, 2024). "There is a genetic component to the disease, which accounts for between 10 and 15% of cases, with several individual genes (such as LRRK2, SNCA, PINK1, PARK7 and PRKN) associated with Parkinson’s disease and over 90 gene loci that can increase the risk of developing Parkinson’s disease." (PMID 38276234, 2024). "Here, we report the same cell-type-specific cilia loss in postmortem brain from Parkinson’s patients with or without LRRK2 pathway mutations." (PMID 39088390, 2024). "DNM3 may be a useful target for the therapy of age-related neurodegenerative diseases, as studies have revealed that genetic variability in DNM3 alters the age of onset for LRRK2 Gly2019Ser Parkinsonism and informs disease-relevant translational neuroscience." (PMID 37666846, 2023). "The study found that 30 studies provided evidence of a relationship between genetics, gene mutations, age, and Parkinson's disease, with 12 studies specifically finding that genetic mutations in SNCA, LRRK2, PARK2, PINK1, DJ1, GBA, and MAPT alleles are associated with the disease." (PMID 36909056, 2023). "LRRK2 is a protein kinase involved in the pathogenesis of Parkinson's disease." (PMID 37845194, 2023). "There have been several documented cases of patients with Parkinson's disease in the absence of Lewy pathology, who have parkin-related disease and in some cases a mutation in the LRRK2 gene." (PMID 37841347, 2023). "Coincidentally, earlier studies show that LRRK2 is a key influencing factor for Parkinson disease (PD), which is significant to be associated with aging, indicating that Myo1b might be involved in the pathogenies of PD through mediating the neural cell senescence." (PMID 36654782, 2023). "Parkinson's Disease is the second most neurological disorder Resihi mushroom has multiple medicinal properties LRRK2 is the one of the most emerging therapeutic target Molecular dynamics and MMGBSA results conclude that Ganoderic Acid A is the most promising compound targeting LRRK2." (PMID 37711263, 2023).